IL23R (interleukin 23 receptor)
Diseases named in the same sentence as IL23R in open-access papers (continued):
Sharing a sentence is not in itself a finding about the gene and the disease.
heart failure (1 paper, 2023). Inability of the heart to pump blood at an adequate rate to meet tissue metabolic requirements. "Another potential multi-disease target that was in top-20 predictions for COPD, PD, and heart failure is IL23R, a receptor for IL-23 pro-inflammatory cytokine." (PMID 37315204, 2023). "According to PandaOmics TargetID platform, APLNR was ranked top-20 for all 4 diseases, while IL23R was ranked top-20 for COPD, PD, and heart failure." (PMID 37315204, 2023).
HIV-1 infection (1 paper, 2017). The type species of lentivirus and the etiologic agent of acquired immunodeficiency syndrome (AIDS). "HIV-1 infection of microbe-exposed LP CD4+ T cells stimulated 3.4-fold higher levels of IL26, a Th17-derived cytokine that has antibacterial properties, and 3.0-fold higher levels of the IL23R, which acts as the receptor of IL23 and helps maintain Th17 cell function." (PMID 28241075, 2017).
hypertriglyceridemia (1 paper, 2025). A laboratory test result indicating elevated triglyceride concentration in the blood. "Patients with hypertriglyceridemia displayed reduced frequencies of CCR6+IL-23R+IFN-γ+ cells, whereas normal HDL levels were associated with CCR6 expression and IL-17A production." (PMID 41300932, 2025). "Patients with hypertriglyceridemia (triglycerides > 150 mg/dL) showed a lower frequency of Th17.1 cells (CCR6+IL-23R+IFN-γ+) compared with those with normal triglyceride levels." (PMID 41300932, 2025).
ileocolitis (1 paper, 2022). Ileocolitis or ileal Crohn's is the most common type of Crohn's disease. "Mechanistically, our data reveal that AIEC-induced epithelial cell ER stress triggers CD103+ dendritic cell production of interleukin-23 (IL-23) and that IL-23R is required for ileocolitis in Agr2−/− mice." (PMID 36384110, 2022). "The authors identify AIEC as a trigger for ER stress, which is required for Th17 ileocolitis and CD103+ DC production of IL-23, and establish the importance of IL-23R signaling for ileocolitis in this model of genetic predisposition to gut inflammation." (PMID 36384110, 2022).
influenza (1 paper, 2015). An acute viral infection of the respiratory tract, occurring in isolated cases, in epidemics, or in pandemics; it is caused by serologically different strains of viruses (influenzaviruses) designated A, B, and C, has a 3-day incubation period, and usually lasts for 3 to 10 days. "In addition, IL-6 is known to activate both STAT 3 and IL-23R expression, which could potentially play a role in IL-17 expression during influenza and S. aureus infection." (PMID 25651926, 2015).
ischemia (1 paper, 2018). A hypoperfusion of the BLOOD through an organ or tissue caused by a PATHOLOGIC CONSTRICTION or obstruction of its BLOOD VESSELS, or an absence of BLOOD CIRCULATION. "Next, IL-23R-Y416FΔICD signaling deficient mice and IL-23R mice were sacrificed after ischemia and 24 h of reperfusion and the hearts were stained for αSMA, HA and Galectin-3." (PMID 30459442, 2018). "Consequently, we challenged the IL-23R (wild-type) and IL-23R-Y416FΔICD signaling deficient mice in open-chest ischemia/reperfusion experiments with 50 min of ischemia and 4 weeks of reperfusion." (PMID 30459442, 2018).
Juvenile onset (1 paper, 2011). Onset of signs or symptoms of disease between the age of 5 and 15 years. "We present evidence for subtype specific association of the IL23R gene with juvenile-onset PsA and ERAP1 gene with the ERA subtype of JIA." (PMID 21281511, 2011).
liver failure (1 paper, 2024). A liver disease characterized by the liver losing or has lost all of its function. "Low levels of mRNA for IL-23R have been reported in human dendritic cells, while IL-23R levels have been found to be elevated in monocytic DCs derived from patients with HBV-related liver failure." (PMID 39796684, 2024).
Löfgren’s syndrome (1 paper, 2020). "On the other hand, the ORs of the risk alleles in IL23R were not affected by the presence of Löfgren’s syndrome or CXR stages." (PMID 32826979, 2020).
lung adenocarcinoma (1 paper, 2021). A carcinoma that arises from the lung and is characterized by the presence of malignant glandular epithelial cells. "Similarly, the expression of the IL23 receptor (IL23R) was also increased upon 5-Aza treatment in the A549 lung adenocarcinoma cell line." (PMID 34901003, 2021).
malaria (1 paper, 2017). Malaria is a serious and sometimes fatal disease caused by a parasite that commonly infects a certain type of mosquito which feeds on humans. "We are currently investigating the impact of multi-haplotypes of IL-23R variants on longitudinal outcomes of malaria including mortality." (PMID 28427357, 2017). "Although IL-23 receptor variation has not been explored in malaria, carriage of rs10889677CC in the IL-23R was associated with increased risk of cancer in Chinese populations." (PMID 28427357, 2017).
multiple myeloma (1 paper, 2024). "It is possible that IL-23R polymorphisms may affect the severity of the disease, the occurrence of bone lesions and the presence of extra-medullary disease in patients with multiple myeloma." (PMID 39796684, 2024). "The IL-23R is expressed on normal plasma cells and on multiple myeloma cells." (PMID 39796684, 2024).
neuropathy (1 paper, 2022). A disorder affecting the nervous system that manifests with pain, tingling, numbness, and/or muscle weakness. "Administration of the IL‐23R antagonist P2305 similarly decreased IL‐23‐induced mechanical sensitivity and decreased mechanical allodynia arising from three separate forms of neuropathy." (PMID 35760453, 2022).
Opportunistic infection (1 paper, 2025). An infection that is caused by a pathogen that would generally not be able to cause an infection in a host with a normal immune system. "This unprecedented efficacy is paired with extremely low side-effects without clinically relevant immune suppression (e.g., opportunistic infections) in clinical trials and real-world observations, which corresponds to the protection of individuals with hypomorphic IL23R function." (PMID 39923740, 2025).
Oral leukoplakia (1 paper, 2025). A thickened white patch on the oral mucosa that cannot be rubbed off. "As IL-23R expression was upregulated in Oral Leukoplakia and Oral Lichen Planus, the therapeutic potential of already clinically available anti-IL23 therapy should be further investigated in these oral lesions." (PMID 40297579, 2025). "In this regard it is interesting that we could observe an increase of IL-23R expression from healthy Controls to Oral Leukoplakia and to OSCC." (PMID 40297579, 2025). "In contrast, Oral Leukoplakia samples showed a significantly (p ≤ 0.032) increased cell density and Labeling Index (LI) of IL-23R and CD68 positive cells compared to Controls (mean IL-23R 64 cells/mm2 vs. 5 cells/mm2 and mean CD68 103 cells/mm2 vs. 8 cells/mm2)." (PMID 40297579, 2025).
osteoarticular tuberculosis (1 paper, 2023). "Additional investigations have revealed that IL23R gene polymorphisms are implicated in osteoarticular tuberculosis among the Guangxi Zhuang population." (PMID 37464360, 2023).
ovarian carcinoma (1 paper, 2016). A malignant neoplasm originating from the surface ovarian epithelium. "Collectively, our findings provide encouraging evidence of a new therapeutic target to inhibit CSCs-mediated ovarian cancer initiation and progression towards the IL-23/IL-23R/STAT3/NF-κB axis." (PMID 27738346, 2016). "To determine whether primary CD133+ CSLCs could also express IL-23 and IL-23R, we utilized immunofluorescence to investigate the expression of CD133, IL-23p19 and IL-23R on in situ ovarian cancer tissue samples." (PMID 27738346, 2016).
pemphigus (1 paper, 2024). Pemphigus is a group of rare autoimmune diseases that cause blistering of the skin and mucous membranes (mouth, nose, throat, eyes, and genitals).This conditioncan occur at any age, but often strikes people in middle or older age. "In line with previous human pemphigus studies, the data presented here confirm the overexpression of IL-17A, IL-17F, IL-17RA, IL-23A, and IL-23R in canine PF skin." (PMID 38393106, 2024).
Pneumocystis infection (1 paper, 2018). "In our experiments, though two groups presented similar frequencies of Th17 cells expressing IL-23R in BALF by flow cytometry, IL-23R mRNA expression in lung and IL-23 concentration in BALF were elevated in IL-9−/− mice during Pneumocystis infection contrasted with WT mice." (PMID 29887863, 2018).
premalignant oral lesions (1 paper, 2018). "The results showed a dependence on IL-23 signaling for the pro-inflammatory state of mice with oral lesions as levels of IL-2, IFN-γ, IL-6, IL-17 and TNF-α were elevated in wildtype mice with premalignant oral lesions, but not in IL-23R KO mice." (PMID 29664967, 2018).
primary Sjögren's syndrome (1 paper, 2012). "The main purpose of this study was to determine the expression of interleukins-17/-23 and receptors of interleukins-17/-23 (IL-17R, IL-23R) focusing on autoimmune epithelitis in patients with primary Sjögren's syndrome." (PMID 22262980, 2012). "The main purpose of this study was to determine the expression of interleukins-17/-23 (ILs-17/-23) and receptors of interleukins-17/-23 (IL-17R, IL-23R) in minor salivary glands (MSGs) of patients with primary Sjögren's syndrome (pSS)." (PMID 22262980, 2012). "In this study, we sought to determine the expression of interleukins-17/-23 (IL-17/-23) and receptors of interleukins-17/-23 (IL-17R, IL-23R) in minor salivary glands (MSGs) of patients with primary Sjögren's syndrome (pSS), with probable preclinical pSS, and with nonautoimmune sicca syndrome." (PMID 22262980, 2012). "Furthermore, we found that the total expression of IL-23R and of IL-23R in glandular ducts, acini, intraglandular interstitium, and infiltrating inflammatory cells was significantly higher in pSS and probable preclinical pSS patients compared with nonautoimmune sicca syndrome patients." (PMID 22262980, 2012).
sacroiliitis (1 paper, 2019). "The rs1004819, located on IL23R, that is associated with MRI sacroiliitis, has proved to be strongly associated with disease susceptibility." (PMID 30646942, 2019). "In this study, rs1004819 located on the IL23R gene was associated with the presence of MRI sacroiliitis and MRI bone oedema size assessed by the SPARCC score." (PMID 30646942, 2019). "Epistatic interactions between the SNP of IL23R and HLA-B27 were investigated to assess whether HLA-B27 allele carriage could interact with the association between rs1004819 and MRI sacroiliitis using two different methods: the RERI method and PLINK epistasis software v1.07." (PMID 30646942, 2019).
squamous cell carcinoma (1 paper, 2013). A carcinoma arising from squamous epithelial cells. "IL-23R levels were significantly induced (p < 0.05) following HDi treatment in the both an adenocarcinoma (A549) and a squamous cell carcinoma (SK-MES-1) cell line." (PMID 23802098, 2013). "Although Gemcitabine is usually given in a combination therapy with cisplatin for squamous cell carcinoma patients, our study has shown that Gemcitabine increases the levels of IL-23R in both NSCLC subtypes." (PMID 23802098, 2013).
Stroke (1 paper, 2014). Sudden impairment of blood flow to a part of the brain due to occlusion or rupture of an artery to the brain. "There was a 3.3 fold non significant increase in IL-23R gene expression in γδT cells in the stroke patients (p>0.05) with a 1.1 fold non significant decrease in IL-23A gene expression (p>0.05)." (PMID 24840735, 2014).
synovitis (1 paper, 2020). Inflammation of a synovial membrane. "However, it is not fully clear which IL‐23R+ T cells are critical in driving T cell‐mediated synovitis." (PMID 31778214, 2020).
tuberculoid leprosy (1 paper, 2016). A principal or polar form of leprosy in which the skin lesions are few and are sharply demarcated. "Our previous studies on stable tuberculoid leprosy had indicated that IL-23 and IL23R but not IL-6 and its receptor (IL-6R) were associated with Th17 cell differentiation." (PMID 27035913, 2016).
typhoid fever (1 paper, 2023). A bacterial infectious disorder contracted by consumption of food or drink contaminated with Salmonella typhi. "Furthermore, an investigation is required to characterize the similar inborn single nucleotide mutations in genes to those discussed here (IL-23R and ZNFX1), which caused recurrent typhoid fever." (PMID 36845636, 2023).
ulcers (1 paper, 2022). "On the other hand, IL23R and IL17 also showed a consistent up-regulation in patients with ulcers compared to the controls." (PMID 35883458, 2022).
Ventricular hypertrophy (1 paper, 2014). Enlargement of the cardiac ventricular muscle tissue with increase in the width of the wall of the ventricle and loss of elasticity. "Gene IL23R is weakly associated (p- value 2.19×10−18) with levels of interleukin 18 but also with adiponectin and ECG measures of ventricular hypertrophy)." (PMID 25329069, 2014).
tumor (50 papers, 2009 to 2025). "High expression of tumor-associated macrophages and cancer stem cell markers contributes to an immunosuppressive tumor microenvironment, potentially intersecting with IL-23/IL-23R signaling." (PMID 39921803, 2025). "Among them, IL23R (interleukin 23 receptor) was associated with prognosis and immune infiltration within the tumor." (PMID 39199659, 2024). "Recently, there has been a significant push to gain a deeper comprehension of the pivotal function of IL-23R variants and the associated pathways in tumor growth and the surrounding tumor microenvironment." (PMID 39796684, 2024). "This is due to the fact that the variant exerts its pro-tumor effects on IL-23R-bearing immune cells, including tumor-associated macrophages (TAMs), natural killer (NK) cells and CD4+ T-helper cells." (PMID 39796684, 2024). "STAT3 from tumor cells and myeloid cells is also known to induce IL-23 production by tumor associated macrophages; regulatory T cells expressing IL-23R are then activated to create an immunosuppressive tumor microenvironment." (PMID 37772080, 2023). "An early study also described heterogeneous IL‐23R expression on tumor‐associated Tregs in a tumor implantation model." (PMID 36444617, 2022). "The elevated expression of IL-23R on tumor cells enhanced tumor-associated inflammation and promoted the development and metastasis of cancer." (PMID 33418929, 2021). "IL-23 is also implicated in the immune response against tumor via the action of the IL-23 receptor (IL-23R)." (PMID 32102441, 2020). "Very interestingly, the expression of tumor-associated genes including vascular endothelial growth factor Vegfa, Il23a, Il23r, and matrix metalloprotease 9 (Mmp9) was almost completely suppressed by the prophylactic administration of ER-464195-01." (PMID 29773794, 2018). "In vivo studies also support the pro-tumour effect of IL-23 and its receptor as underlined by work on knock-out mice (IL-23R-/- or IL-23p19-/-) showing marked growth-restriction in transplanted tumours and reductions in angiogenesis." (PMID 25015728, 2014). "The clinical features analysis demonstrated significant associations between rs1884444 in IL23R and human epidermal growth factor receptor 2 (Her-2) and tumor size status." (PMID 23239971, 2012). "By contrast, deficiency in IL-23 or the IL-23R not only dramatically reduces tumor incidence but also reduces tumor growth of established tumors." (PMID 20885915, 2010). "Collectively, these data suggest that IL-23R-deficient Treg cells protect mice from MC-38-mediated sporadic colorectal carcinogenesis, likely via increased intratumoral pro-inflammatory macrophages that promote anti-tumor immunity." (PMID 38375204, 2023). "In addition, we showed that IL17F and IL23R polymorphisms were positively associated with colon tissue mostly associated to colon location of the tumor." (PMID 26083022, 2015). "Furthermore, IL23R, GnRHR, and beta-catenin, linked to the GnRH pathway, were upregulated in patient-derived tumour tissue samples and their expression correlated to several unfavourable clinical parameters." (PMID 22173670, 2012). "More than 50% of IL-23R-positive cells co-expressed myeloid markers, suggesting an active role of the IL-23/macrophage axis in the tumor microenvironment." (PMID 40944094, 2025). "More than 50% of IL-23R-positive cells co-expressed myeloid markers, suggesting an immunomodulatory role of the IL-23/macrophage axis in the tumor microenvironment of oral precursor lesions." (PMID 40944094, 2025). "Although we found that other T cell subsets express IL-23R, specific ablation of Il23r in Treg cells resulted in reduced tumor growth, phenocopying full Il23r-KO mice." (PMID 38356059, 2024). "We found that tumor volume and weight were drastically reduced in Il23rdel/del mice compared to in Il23rfl/fl mice in all three tumor models, thus confirming the previously reported protumorigenic function of IL-23/IL-23R signaling." (PMID 38356059, 2024).